CYCSP39 (CYCS pseudogene 39)
Synonyms: HC1; HCP39
Gene: Processed pseudogene on chromosome 16 (25,454,339 to 25,454,647, reverse strand). Ensembl gene ENSG00000260690.
Diseases named in the same sentence as CYCSP39 in open-access papers:
CYCSP39 is named in the same sentence as 6 diseases in open-access papers, as found by Europe PMC text mining. Sharing a sentence is not in itself a finding about the gene and the disease.
CYCSP39 shares sentences with these, for which no sentence is quoted: breast carcinoma (2 papers); tumor (2); cancer (1); infection (1); sarcoma (1); sitosterolemia (1).